FLT3 (fms related receptor tyrosine kinase 3)
Diseases named in the same sentence as FLT3 in open-access papers (continued):
Sharing a sentence is not in itself a finding about the gene and the disease.
leukemia (continued). "Growth factors and cytokines in bone marrow (BM) microenvironment supporting the survival of residual leukemia cells during FLT3 inhibitor treatment confer primary drug resistance." (PMID 36691065, 2023). "Circ-MYBL2 promotes proliferation and cell-cycle progression and inhibits apoptosis of FLT3-ITD+ leukemia cells." (PMID 37124518, 2023). "In order to define the loss of stemness in more detail, we performed multi-parametric single-cell immunophenotyping of bone marrow cells derived from the FLT3-ITD driven leukemia model." (PMID 37587260, 2023). "All patients with FLT3-ITD (n = 3), KMT2A-rearranged (n = 6), and IDH mutations (n = 3) were classified as having a leukemia response to AQ." (PMID 36831684, 2023). "Further, we found that CG-806 achieved its anti-leukemia activity in FLT3-mutated AML and FLT3-WT AML through different mechanisms." (PMID 36865133, 2023). "Our findings demonstrate that expression levels of FLT3-ITD and also cell proliferation decrease upon ex vivo revumenib treatment of patient-derived NUP98::NSD1/FLT3-ITD+ AML cells suggesting that the NUP98 fusion is the main driver of leukemia development." (PMID 37520776, 2023). "Collectively, the results of the epigenetic profiling, the chromatin interaction, and the expression correlation suggest that there is h-FLT3-mediated transcriptional activation of FLT3 in MLL-r leukemia cells." (PMID 38016946, 2023). "A recent study showed that the combined mutation of NPM1/TET2/FLT3-ITD and DNMT3A observed in about 4% of NPM1-mut AMLs resulted in an aggressive leukemia phenotype." (PMID 37509445, 2023). "Our prior pre-clinical work with AQ also demonstrated enrichment of KMT2A-rearranged and FLT3-ITD leukemias amongst AQ-responsive patient leukemia samples." (PMID 36831684, 2023). "We identified a series of HOXA9-driven cis-regulatory elements that are critical for the survival of MLL-r leukemia cells, including h-FLT3, a distal enhancer critical for the high expression of FLT3 in MLL-r leukemia and its survival." (PMID 38016946, 2023). "A loss of circ-MYBL2 in mutant cells resulted in a decline in FLT3 phosphorylated kinases and impairment of STAT5 phosphorylation, a key downstream protein of oncogenic FLT3 and crucial for aberrant leukemia cell growth." (PMID 37124518, 2023). "These facts suggest that selective FLT3 inhibition in leukemia cells can block excessive FLT3 leukemia activation with acceptable hematopoietic side effects." (PMID 36612249, 2022). "which was reflected in spleen weight, white blood cell count and proportion of WBC expressing GFP, indicating the dependence of these tnFGFR1 expressing leukemia cells on FLT3 and providing a possible targeting strategy for this leukemia." (PMID 35906694, 2022). "As a tyrosine kinase, FLT3 represents an attractive therapeutic target, and the therapeutic effects of inhibiting FLT3 have been explored in leukemia, particularly in AML with FLT3 ITD7,22,28–33." (PMID 36104354, 2022). "Inhibition of proliferation and colony formation in FLT3-ITD mutant leukemia cells by reducing DOCK2 expression." (PMID 36250020, 2022). "Consistently, in this leukemia subgroup a higher prevalence of mutations was detected that are typically associated with AML, including FLT3 mutations." (PMID 35626079, 2022). "The combination of menin and FLT3 inhibitors significantly reduced leukemia burden and induced the long-term remissions in a PDX model with both NPM1 and FLT3-ITD mutations." (PMID 36237321, 2022). "AML is the most common leukaemia type (32% of all types of leukaemia patients); 30% of AML patients elicited a mutation in Fms-like tyrosine kinase 3 receptor (FLT3)." (PMID 35745866, 2022). "FLT3 was chosen as the target antigen in our study for inciting antitumor activity due to the high correlation between FLT3 and leukemia; however, there are many other TAAs that have yet to be discovered in blood cancers." (PMID 35686131, 2022).
leukemia (continued). "Recently, we showed that FLT3-N676K mutation has stronger transforming activity than FLT3-ITD, but leukemia induced by FLT3-N676K showed 100-fold less LSC frequency than FLT3-ITD." (PMID 34732858, 2022). "Mutated FLT-3 proteins are involved in activating several signaling pathways, for example MAPK/ERK and STAT5, and thus indicate a higher risk of developing leukemia as well as a worse prognosis." (PMID 36120561, 2022). "In this study, we utilized MRX-2843—a dual MERTK/FLT3 inhibitor currently in clinical trials—to probe the anti-leukemia effects of MERTK inhibition in ETP-ALL and T-ALL models." (PMID 36551626, 2022). "These synergism-motivated studies in mouse models which showed that FLT3 inhibition combined with T cell infusion can lead to complete elimination of leukemia cells." (PMID 35460465, 2022). "Genes significantly upregulated by tnFGFR1 include Flt3 and Kit which promote a leukemia stem cell phenotype." (PMID 35906694, 2022). "In the AML_GSE116256 dataset, FLT3LG is mainly expressed in CD4+ T cells, but compared with the PBMC_30K_10× dataset, the expression level of FLT3LG is remarkably reduced, and FLT3 is mainly expressed in leukemia cells and precursor cells." (PMID 36081495, 2022). "Given the correlation between tnFGFR1 and FLT3 expression, however, application of FLT3 inhibitors can potentially overcome this resistance and provide a novel treatment option for related leukemias." (PMID 35906694, 2022). "This phenomenon also happens in the anti-FLT3 therapeutic antibody IMC-EB10, which shows good efficacy against leukemia cells with mutated FLT3 in preclinical study, but fails to show efficacy in clinical phase 1 trial." (PMID 35999600, 2022). "CDDD11-8 displayed antiproliferative activity against leukemia cell lines, and particularly potent effects were observed against MV4-11 and MOLM-13 cells, which are known to harbor the FLT3-ITD mutation and mixed lineage leukemia (MLL) fusion proteins." (PMID 35267421, 2022). "Using a more elaborate proliferation assay, we observed complete inhibition for both FLT3-ITD/MLL-AF9 or only MLL-AF9-positive leukemia cell lines generated by oncogene transduction of murine bone marrow stems cells." (PMID 35326163, 2022). "Blocking GAB2 function or expression would be superior to targeting FLT3 directly, since the docking protein serves downstream of various leukemia-relevant RTKs." (PMID 34903841, 2022). "The overexpression of PRMT5 leads to an increase in leukemia cell growth, especially in FLT3-ITD primary blasts compared to FLT3-WT patients." (PMID 36358861, 2022). "The Flt-3/Flt-3L signal path has been gaining importance recently in the treatment of both solid tumors and leukemias." (PMID 36010838, 2022). "Combining treatment with DOCK2 knockdown and DDR inhibitors such as CHK1 inhibitor MK876, WEE1 inhibitor MK1775, and RAD51 inhibitor 1302 significantly enhanced the sensitivity of mice with FLT3-ITD mutant leukemia cells to cytarabine." (PMID 36250020, 2022). "On the other hand, the treatment with the DNMT3A and FLT3-siRNA nanocarriers reduced the percentage of circulating hCD45-positive leukemia cells, which was compared on day 12 after treatment." (PMID 36457063, 2022). "We previously have identified the aurora kinases (AURKs) and FMS-like tyrosine kinase 3 (FLT3) multikinase inhibitor DBPR114 exhibiting broad spectrum anti-tumor effects in both leukemia and solid tumors." (PMID 35062934, 2022).
leukemia (continued). "Additionally, in all ITD mutations of the FLT3 gene, agarose gel electrophoresis analysis demonstrated the presence of both mutated and wild-type alleles, indicating mutation heterozygosity in correspondence with previous reports of canine leukemia patients and cell lines." (PMID 36072760, 2022). "NK-92/4G8.28.z cells were specifically activated by FLT3+ leukemia cells in vitro and significantly delayed disease development in an aggressive leukemia xenograft model." (PMID 35493522, 2022). "In mice xenografted with FLT3-ITD + AML cells, co-treatment with oral FLT3 and autophagy inhibitors synergistically impaired leukemia progression and extended overall survival." (PMID 35999260, 2022). "Cells transformed with tnFGFR1 are insensitive to FGFR1 inhibitors but treatment of these cells with the Quizartinib (AC220) FLT3 inhibitor, suppresses in vitro growth and development of leukemia in vivo." (PMID 35906694, 2022). "Targeted suppression of autophagy with CQ enhanced the anti-leukemia effect of FLT3 inhibitors, and eliminated acquired resistance mediated by acquired D835Y mutation or MSCs." (PMID 35794565, 2022). "The correlated expression of tnFGFT1 with Kit and Flt3 were confirmed using flow cytometry of primary leukemia cells from the mouse models." (PMID 35906694, 2022). "Researchers showed that Sorafenib increased IL-15 production by FLT3-ITD leukemia cells, which in turn caused an increase in CD8+CD107a+IFN y T cells which eradicated leukemia in secondary recipients." (PMID 36530990, 2022). "Out of 17 genes that mapped to the DISEASE database, 7 have been linked to pathogenesis of human CLL and/or other leukemias (Birc3, Wnt5a, SP140, Atr, Lyn, CD274, and Flt3), and SIFT analysis revealed that the detected mutation in Lyn is likely deleterious." (PMID 34417556, 2022). "Here we clearly demonstrated that the VRP-FLT3 vaccination overcame the intrinsic self-tolerance mechanisms to induce a strong antibody response to FLT3 in the tumor-bearing mice in both of our leukemia and lymphoma models." (PMID 35686131, 2022). "To identify the suitable preclinical model, we first evaluated the growth inhibitory effect of ASP1235 on several leukemia cell lines expressing FLT3 and found that THP-1 cells were partially sensitive to ASP1235 in vitro." (PMID 36537913, 2022). "Autophagy activation decreased the suppression efficacy of FLT3 inhibitors on FLT3 downstream signaling and then weakened their anti-leukemia effect." (PMID 35794565, 2022). "A PDX model study suggested that inflammatory genes were upregulated in quizartinib-resistant FLT3-mutant leukemia, and co-administration of dexamethasone with quizartinib showed synergistic cell death in vivo." (PMID 35216478, 2022). "Due to its prominent involvement in leukemia, FLT-3 specific inhibitors, such as quizartinib, are being used to treat AML, either unaccompanied or in combination with other treatments." (PMID 36120561, 2022). "Preclinical studies evaluating the double targeting of FLT3 with CAR-T cells and the FLT3 inhibitor gilteritinib seem to suggest potent leukemia clearance and normal HSC protection." (PMID 36612249, 2022). "Future directions in CAR-NK research will involve novel targets such as fms-like tyrosine kinase 3 (FLT3) for leukemia as well as CD138 and CCND subset 1 (CS1) for multiple myeloma." (PMID 36613644, 2022). "More recently, the combined inhibition of menin-MLL (MLL1, KMT2A) and FLT3 demonstrated a synergistic therapeutic opportunity in these leukemia subtypes." (PMID 35387132, 2022). "First, in AML, the expression of Fms-related tyrosine kinase 3-internal tandem duplications (FLT3-ITD), a common driver mutation in leukemia, reduces AraC sensitivity by lowering ENT1 levels." (PMID 33652766, 2021). "USP10 inhibition by HBX19818 shows anti-leukemia effect in FLT3-ITD positive AML cells and mouse models." (PMID 34454635, 2021).
leukemia (continued). "Another USP10 inhibitor, Wu-5, also shows anti-AML effect and overcomes FLT3 inhibitor resistance and synergistically enhances the anti-leukemia effect of crenolanib through targeting both FLT3 and AMPKα pathway." (PMID 34454635, 2021). "The MV4-11 cell line is a FLT3-ITD mutant leukemia cell line which is often used in research related to FLT3-ITD AML." (PMID 33796529, 2021). "Further studies investigating ADCC with alemtuzumab, and the anti-tumor effects of alemtuzumab in a xenograft model using more patient samples will be needed to validate our proposed treatment strategy for FLT3-ITD leukemia." (PMID 34035227, 2021). "Although both factors regulate PIM1 expression, the FLT3-ITD axis is more sensitive and is responsible for PIM1 downregulation with low-dose DOT1L inhibitor treatment in MLL-r leukemia also bearing the FLT3-ITD mutation." (PMID 34263728, 2021). "Inhibition of USP9X by its inhibitor WP1130 or G9 shows potent anti-leukemia effects in FLT3-ITD-driven cells by blocking downstream signaling events of FLT3." (PMID 34454635, 2021). "IDH2 mutations cooperate with mutations in other genes such as Dnamt3a−/−, NPMc+, NrasG12D, and Flt3-ITD to induce leukemia in mice." (PMID 34944812, 2021). "To further interrogate the H3K79me2-dependence of leukemia survival on FLT3-ITD/STAT5A signaling, we sought to ectopically restore this signaling pathway upon DOT1L inhibition to potentially rescue viability." (PMID 34263728, 2021). "Our observations suggest that most of the toxicity from low-dose DOT1L inhibition in MLL-r, FLT3-ITD+ leukemia cell lines stems from downregulation of FLT3 and subsequent loss of STAT5A phosphorylation." (PMID 34263728, 2021). "Several mechanisms have been described, including, but not limited to, the emergence of clones that are resistant to FLT3 inhibitors being used, but also the protection of leukemia cells by the microenvironment." (PMID 34070902, 2021). "In summary, this study exhibits a novel report of Dox–Cur co-treatment in both enhancing cytotoxicity of Dox and inhibiting cell proliferation via FLT3 protein expression in leukemia stem cells and leukemic cells." (PMID 34641328, 2021). "Withal, inhibition of leukemia cell proliferation was observed by in vivo evaluation of FLT3-CAR T cell function." (PMID 34412685, 2021). "As a result, prominent anti-tumor cytotoxicity of CAR T cell against FLT3+ leukemia cells as well as the influential killing of the ITD type FLT3 cells compared to the wild type FLT3 cells was observed by using the CAR T cell." (PMID 34412685, 2021). "DBF activates the expression of genes encoding the proteins involved in leukemia cell survival, such as KIT, CTNNB1, CCNE1, NFKB1, E2F1, and downregulates the expression of CCND2, CCNA1, and FLT3 genes." (PMID 34564151, 2021). "Taken together, the findings of this study revealed CD52 as a molecular target for the antibody treatment of FLT3-ITD leukemia." (PMID 34035227, 2021). "The JAK-STAT pathway is believed to be one of the FLT3 downstream pathways in leukaemia and the claim was strengthen by a report of upregulated STAT5 phosphorylation following FL stimulation in MLL-rearranged leukaemia." (PMID 33581643, 2021). "The effects of post-transplant sorafenib is multifaceted, including direct FLT mutation inhibition, GVL effect augmentation through IL-15 production in FLT3-ITD mutant leukemia cells, and also synergic effects with alloreactive T cells." (PMID 35155192, 2021). "Our mechanistic studies provide impetus for exploration of these ideas in pre-clinical or patient-derived FLT3-ITD or MLL-PTD leukemias." (PMID 34263728, 2021). "Since alemtuzumab is an approved drug, further clinical studies using alemtuzumab are warranted to evaluate our proposed treatment strategy for FLT3-ITD leukemia." (PMID 34035227, 2021). "FL/FLT3 pathway-directed STAT5 activation leads to increased expression of MCL-1, a hallmark biomarker of leukemia stem cells." (PMID 33691697, 2021).
leukemia (continued). "In FLT3-wt leukemia cell lines (THP-1 and RS4-11), the wild-type receptor was mainly found at the PM." (PMID 34811450, 2021). "DOT1L inhibition reduces STAT5A activation and downregulates STAT5A targets in FLT3-ITD leukemia lines." (PMID 34263728, 2021). "Orally administered KX2-391 significantly prolonged the survival of a murine leukemia model induced by FLT3-ITD-F691L." (PMID 34217323, 2021). "Due to this unresolved clinical issue, we tested navitoclax and hydroxyurea on Ba/F3 leukemia cells with FLT3-ITD (FLT3 with internal tandem duplication at 598) and therapy-associated FLT3-ITD/TKD mutants (FLT3-ITD+D835Y and FLT3-ITD+N676K)." (PMID 34298678, 2021). "We found 2007 genes upregulated with 100 nM pinometostat treatment, including many MHC class II genes with large fold-changes that significantly overlapped with a set of genes consistently downregulated in FLT3-ITD+ (KN) leukemia samples." (PMID 34263728, 2021). "Although the enhancement of the cytotoxicity of FLT3 inhibitors with HDAC inhibitor dacinostat was registered for MV-4-11 cells and primary leukemia cells, this effect was specific for AML cells harboring FLT3 activating mutation." (PMID 34944663, 2021). "Metformin also plays an anti-leukemia role by activating p-AMPK and cooperatively sensitizes FLT3-mutated AML to sorafenib." (PMID 34659343, 2021). "We investigated the combination of FLT3 TKIs (Gilteritinib or Sorafenib), with Venetoclax, a BCL-2 selective inhibitor (BCL-2i), on FLT3/ITD leukemia cells." (PMID 34024909, 2021). "Approximately two-thirds of CBF leukemia cases harbor activating mutations in NRAS, KIT, FLT3, KRAS, PTPN11, and/or loss-of-function mutations in NF1." (PMID 34331016, 2021). "GC treatment combined with dual inhibition of FLT3 and SFKs with our previously developed compound RK-20449 led to reduction of GC-resistant human leukaemia cells in the MLL-ALL engrafted mice." (PMID 33581643, 2021). "Unlike MV4;11, the MOLM13 cell line harbors an MLL-AF9 translocation and is heterozygous for the FLT3-ITD mutation, lesions that have been shown to cooperate to reduce the latency of leukemia onset in mice." (PMID 34263728, 2021). "This pathway also depends on MLL1, indicating combinations of DOT1L, MLL1 and FLT3 inhibitors should be explored for treating FLT3-mutant leukemia." (PMID 34263728, 2021). "Our results indicate common deregulated pathways among these leukemias, opening the way to study the role of this biomarker in order to predict responses to FLT3 inhibitors in wild-type FLT3 AML." (PMID 33592069, 2021). "Studies have shown that the CHK1 inhibitor MK-8776 can significantly increase the sensitivity of leukemia cells to histone deacetylase inhibitors by disrupting the mechanisms of DNA replication and DNA repair, including FLT3-ITD + leukemia cells." (PMID 34168220, 2021). "Especially, FLT3 signaling activity was increased in MLL-leukaemia cells leading to constitutive activation of FLT3 downstream signaling pathways." (PMID 33581643, 2021). "For example, individuals with FLT3-mutated AML have high amounts of β-catenin, promoting in vivo leukemia growth in xenograft mice reconstituted AML cell lines with del(5q)." (PMID 34953494, 2021). "In contrast, we employed genome editing, permitting the construction of a FLT3-ITD-containing leukemia cell model that more closely resembles the actual condition of leukemia cells in patients." (PMID 34035227, 2021). "This study aims to explore the underlying mechanism of combining Gilteritinib with ATO at low concentration in the treatment of FLT3-ITD positive leukemias." (PMID 32565734, 2020). "This is supported by the work demonstrating that NUP98-HOXD13 expression in hematopoiesis induces leukemia with long latency, suggesting that additional cooperative genetic events like mutated NRAS, KRAS, and FLT3 reduce the disease latency." (PMID 32993115, 2020). "Therefore, TKD mutations could only partially explain leukaemia relapse after FLT3 inhibitors." (PMID 32102366, 2020).